USP14 (ubiquitin specific peptidase 14)
Diseases named in the same sentence as USP14 in open-access papers (continued):
Sharing a sentence is not in itself a finding about the gene and the disease.
cancer (continued). "We examined the expression levels of vimentin and USP14 in our GC sample cohorts by RT-qPCR and found higher expression levels in cancer compared with the paired adjacent normal tissues." (PMID 27448976, 2017). "Our previous reports have shown that PtPT induces accumulation of Ub-prs due to inhibition of UCHL-5 and USP14 in other cancer cells." (PMID 28619062, 2017). "This novel nickel complex can also target proteasomal DUBs (UCHL5 and USP14) and induce apoptosis in cancer cells." (PMID 29039082, 2017). "SiRNA interference studies on the three DUBs in cancer cells suggested that RNAi of USP14 can inhibit cellular protein degradation." (PMID 27448976, 2017). "In order to test the long-term effect of USP14 inhibition or silence on cancer cells, we measured colony formation of LNcap cells using IU1 at 50 μM or stably expressing USP14 shRNA." (PMID 28151478, 2017). "USPs, such as USP1, USP2, USP7, USP9x and USP14, were recently shown to contribute to the development of cancer and are emerging as novel cancer drug targets." (PMID 27780924, 2016). "b-AP15 has been reported to be a highly selective USP14 inhibitor that has already shown promising anti-cancer activities." (PMID 26639022, 2015). "Ubiquitin‐specific protease 14 (USP14) is a member of the USP family responsible for the catalytic removal of ubiquitin (Ub) from proteins directed to the proteasome, implicated in the pathogenesis of neurodegeneration and cancer." (PMID 40095364, 2025). "Among these cancers, 14 demonstrated significant dysregulation of USP14 transcription level." (PMID 39928282, 2025). "Similarly, colony formation assays indicated that USP14 knockdown impaired the clonogenic ability of cancer cells, which was restored by BAG4 overexpression." (PMID 40316942, 2025). "Besides, previous studies have also demonstrated that USP14 is involved in the occurrence and progression of certain cancers and neurodegenerative diseases." (PMID 40662581, 2025). "Contemporary research has revealed the overexpression of USP14 in many types of cancer." (PMID 39928282, 2025). "Additionally, several studies have identified an overexpression and amplification of USP14 in cancer, which has been correlated with a reduced survival rate." (PMID 38383348, 2024). "In addition, the activation of Nrf2 appears to promote USP14 expression, given that USP14 levels are correlated to Nrf2 levels across cancer types, oxidative stress and the disruption of the Keap1/Nrf2 interaction promote USP14 expression." (PMID 39430244, 2024). "USP14 removes ubiquitin from vimentin to promote cancer in gastric cells." (PMID 39605891, 2024). "Since the discovery, the DUB family member USP14 has been primarily explored in cancer progression." (PMID 38909015, 2024). "To conclude, USP14 expression was elevated in various cancers." (PMID 37082728, 2023). "As Degrasyn (a selective inhibitor of USP5, USP9X, and USP14) has shown an inhibitory effect on some cancer types, our aim was to determine whether Degrasyn could be a potential therapeutic agent in BC." (PMID 36979739, 2023). "Therefore, USP14 can be used as a novel drug target for cancer treatment, and the development of its inhibitors is a new direction for antitumor drug research." (PMID 37082728, 2023). "Additionally, in tumor-bearing mice, IU1 inhibits USP14, which impairs the suppressive action of cancer-promoting macrophages and significantly alters the composition of the immune microenvironment." (PMID 37658402, 2023). "Interestingly, accumulated studies have suggested that USP14 acts a pivotal protein in mediating cancer progression by affecting tumor cell proliferation, migration and angiogenesis." (PMID 37917013, 2023). "Therefore, we hope that existing studies on USP14's role in innate immunity can guide future research on metabolic immunity and cancer immunotherapy." (PMID 37658402, 2023).
cancer (continued). "Despite the promising findings on USP14's role in innate immunity and relatively mature inhibitor development, research linking USP14 to tumor immunity and the applicability of USP14 inhibitors in cancer immunotherapy is still limited." (PMID 37658402, 2023). "As a DUB family member, USP14 is aberrantly expressed in various kinds of cancer." (PMID 36693850, 2023). "Although USP14 activity ameliorates pathological changes in this cancer model through inactivation of the proteasome, USP14 can also have pro-malignant effects in other cancer types." (PMID 34689261, 2022). "They extracted nobiletin from citrus peel, a type of polymethoxylated flavonoid, which induced cancer cells to block in the G0/G1 phase and prevented the interaction of AR-V7 with ubiquitin specific peptidase 14 (USP14) and USP22, so as to selectively stimulate the proteasome destruction of AR-V7." (PMID 36230800, 2022). "To determine whether USP14 plays a role as a regulator of endogenous FASN levels in cancer cells in the same manner as MPHs, we transfected various cancer cell lines with siRNA targeting USP14." (PMID 34948233, 2021). "Since the dysregulation of USP14 has been implicated in multiple human cancers, USP14 inhibitors may be also applicable to treat other cancers with altered USP14 activity." (PMID 33791305, 2021). "The inhibition of USP14 can be speculated to be particularly cytotoxic to cancer cells as it could block proteasome function and increase proteasomal substrates." (PMID 33791305, 2021). "Based on these reports, many studies have suggested that USP14 inhibitors alone or in combination with other anticancer drugs might be potent cancer therapeutics." (PMID 34948233, 2021). "As a therapeutic target, USP14 has been best studied in neurological disorders and cancers." (PMID 34207520, 2021). "For example, UCHL5/USP14 suppresses apoptosis and autophagic cell death to promote cancer." (PMID 33919439, 2021). "Besides the USP14 oncogenic role in human cancers, its role in neurodegenerative disorders has been extensively investigated." (PMID 34089575, 2021). "By contrast, it remains to be seen whether anti-cancer effects by USP14 inhibitors can be also mediated, at least in part by enhanced proteasomal degradation." (PMID 34207520, 2021). "Moreover, our data also imply that high USP14 levels can predict radiosensitivity in cancer patients." (PMID 31740976, 2020). "Downregulated ubiquitin-specific protease 14 (Usp14) could be regarded as a biomarker for cancer invasion and metastasis, since it is known to be upregulated in various cancer types, including colorectal." (PMID 32973493, 2020). "USP14 is abundantly present in most cancers and mediates proteasome activity in cancer cells." (PMID 31653087, 2019). "USP14 inhibition has been considered a therapeutic strategy for accelerating degradation of aggregation-prone proteins in neurodegenerative diseases and for inhibiting proteasome function to induce apoptotic cell death in cancers." (PMID 31703099, 2019). "Recent studies have shown that USP14 participates in cell signaling transduction via regulating the turnover of its specific substrates, which in turn have important functional consequences in neuroglial diseases and cancers." (PMID 30425250, 2018). "The results showed that the mut-USP14 still had a partial effect in promoting the malignant behavior of GC, which may be because USP14 acts on proteasomes and may also affect the signaling pathways of the cancer cells." (PMID 27448976, 2017). "The expression of USP14 is increased in a variety of cancers." (PMID 29186924, 2017). "Others like USP14 inhibitor (i.e., IU1) are proposed as a therapeutic approach for neurodegenerative diseases or specific tumors by promoting the degradation of neurotoxic or cancer-causing proteins." (PMID 29039082, 2017). "Next, we verified the biological function of USP14 in cancer progression related to autophagy." (PMID 29326710, 2017).
cancer (continued). "USP14 has been reported as an oncogene in different types of cancer, including GC." (PMID 27448976, 2017). "Moreover, studies have shown high USP14 expression in several kinds of tumors; USP14 exerts a widespread influence on cell proliferation, apoptosis, and tumor metastasis, indicating it as a novel therapeutic target in cancer." (PMID 29039082, 2017). "Overexpression of USP14 or UCHL5 was observed in several carcinomas." (PMID 28619062, 2017). "This, along with previously published reports showing that USP14 expression levels fluctuate within cancer cells as they progress through the cell cycle, suggests that highly proliferating cells may have greater dependence on USP14 activity." (PMID 27121063, 2016). "This suggests increased USP14 expression levels could be either a requirement for or a consequence of cancer cells' proliferation and of tumor aggressiveness in vivo." (PMID 27121063, 2016). "Interestingly, examination of gene expression profiles of different cancer cell lines (Broad-Novartis Cancer Cell Line Data Base) showed that USP14 and UCHL5 are both strongly expressed in MM cells." (PMID 27264969, 2016). "Recently, we have reported that the anti-cancer activity of copper (II) pyrithione CuPT and gold (I) complex auranofin is tightly associated with their ability to target and inhibit the 19S proteasome-associated deubiquitinases (DUBs), UCHL5 and USP14." (PMID 26097878, 2015). "Recently, we have reported that the anti-cancer activity of copper (II) pyrithione CuPT and gold (I) complex auranofin is associated with targeting the 19S proteasome-associated deubiquitinases (DUBs), UCHL5 and USP14." (PMID 26097878, 2015). "USP14 may hinder mitophagy, resulting in the accumulation of damaged mitochondria, which can drive metabolic reprogramming and increase chemosensitivity, key factors in cancer progression and therapy resistance." (PMID 40316942, 2025). "Interestingly, USP14 plays a role in the immune therapy of cancers." (PMID 37917013, 2023). "Thus, to fully understand the signaling pathways and the interactomes of USP14 involved in cancer cell growth and metabolism, further research on the phosphorylation of USP14 by AKT along with inhibition and knockdown studies of USP14 may be necessary." (PMID 34948233, 2021). "In this study, we hypothesized that the compensatory adaptive response of lipid metabolism by FASN inhibitors in cancer cells can be counteracted by reducing FASN levels using IU1, a USP14 inhibitor, and therefore inhibiting FASN and USP14 together will dramatically suppress the cancer cell growth." (PMID 34948233, 2021). "In addition, USP14 overexpression reduced the FASN protein level in cancer cells." (PMID 34948233, 2021). "However, the effect of USP14 on the function or stability of FASN in cancer cells is completely unknown." (PMID 34948233, 2021). "Hence, we hypothesized that the regulation of FASN levels by USP14 is a minor indirect effect and that the regulation of cancer proliferation by USP14 is through a pathway other than the FASN-controlled de novo lipogenesis pathway." (PMID 34948233, 2021). "Therefore, it will be interesting to explore whether USP14 could regulate FASN protein stability in cancer cells to promote tumorigenesis." (PMID 30425250, 2018). "However, an understanding of the role of USP14 in cancer biology is still very limited." (PMID 23702845, 2013). "The findings indicate that USP14 stabilizes BAG4, which restricts Parkin recruitment to mitochondria and consequently suppresses mitophagy in cancer cells." (PMID 40316942, 2025). "USP14 and UCHL5, members of the DUB family, have been observed to be upregulated in various cancers, playing significant roles in tumor progression." (PMID 40804247, 2025). "CCK8 assays demonstrated that knockdown of USP14 led to a significant reduction in cell viability by 37% (LoVo) and 32% (SW48) at 72h, suggesting its critical role in supporting cancer cell proliferation." (PMID 40316942, 2025).
cancer (continued). "In conclusion, the data indicate that BAG4 is crucial in USP14-driven tumorigenesis and chemosensitivity in CRC, significantly influencing cancer progression and oxaliplatin treatment response." (PMID 40316942, 2025). "USP14 belongs to the USP family member of DUBs superfamily, which has been shown to be involved in the regulation of neuron diseases, cancer, as well as viral proliferation." (PMID 40662581, 2025). "The study underscores the therapeutic promise of targeting the USP14/BAG4/PRKN axis to boost mitophagy and increase cancer cell sensitivity to chemotherapy, especially oxaliplatin." (PMID 40316942, 2025). "Herein, we screened a series of DUBs to observe their protein expression under PDGF-BB stimuli and found that USP14 expression was increased significantly; (iv) USP14 is a DUB primarily reported in cancer development." (PMID 38909015, 2024). "We also revealed the protein connections between USP14, HK2, and P62 and elucidated the potential mechanisms driving cancer development." (PMID 38383348, 2024). "We previously reported that USP14 was significantly overexpressed in OSCC and that knockdown of USP14 markedly inhibited tumor growth and triggered apoptosis in cancer cells." (PMID 38388430, 2024). "Ubiquitin-specific protease 14 (USP14), a member of the USP family, which catalyzes ubiquitin cleavage from a range of protein substrates, has been found dysregulated in several cancers." (PMID 37917013, 2023). "Forty-five tissue samples from patients with HNSCC cancer were collected to determine the correlation of USP14 and HSF1 expression in the diagnosis of HNSCC, which is a novel mechanism of USP14 as a carcinogenic gene in HNSCC." (PMID 37686660, 2023). "USP14 was found to modulate the expression of TAZ downstream target genes through a feedback mechanism and ultimately promoted cancer progression and liver metastasis in PDAC models in vitro and in vivo." (PMID 35906484, 2023). "WP1130 (USP5, USP9X, USP14, and UCH37 inhibitors) can ubiquitinate ULK1 and restrain autophagic flux, which decrease many cancer cells’ progression and metabolism." (PMID 37190313, 2023). "Proteasomal deubiquitinases (USP14 and UCHL5) have fundamental roles in the ubiquitin‐proteasome system and possess multiple functions during cancer progression." (PMID 36082692, 2022). "In this study, we found that increased expression of the proteasomal deubiquitinase USP14 and UCHL5 in primary cancer cells from CML patients compared to healthy donors." (PMID 36082692, 2022). "In the last decade, elucidating the role of many USPs, such as USP2, USP7, USP10, USP22, USP44, USP9X, and USP14, in different cancers led to the development of inhibitors for USP7, USP14, USP1, and USP9X." (PMID 34758854, 2021). "Since USP14 reduced FASN protein levels in cancer cells, it was necessary to confirm the deubiquitination of FASN by USP14." (PMID 34948233, 2021). "USP family members play different functions in cancer, and most of them, such as USP1, USP2, USP7, USP14, and USP17, contribute to cancer promotion." (PMID 33619866, 2021). "Surprisingly, USP14 rather reduced the protein levels and activity of FASN in cancer cells, although it slightly inhibited the ubiquitination of FASN." (PMID 34948233, 2021). "UCHL5 (or UCH37), USP14 and POU1 (Rpn11) are the three DUBs of the 19S proteasome that have been massively investigated and targeted due to their great potency on cancer cells." (PMID 32272746, 2020). "b-AP15, a selective small molecule inhibitor of proteasomal USP14 and UCHL5 deubiquitinases (DUBs), has shown selectivity and efficacy in several other types of cancer cells." (PMID 31694672, 2019). "Recently, a novel small molecule b-AP15 is identified as an inhibitor of the USP14/UCHL5 (DUBs) of the 19S proteasome, resulting in cell growth inhibition and apoptosis in several human cancer cell lines." (PMID 28968984, 2017).
cancer (continued). "Selective inhibition of USP14 and UCHL5 by b-AP15 or auranofin has been developed as a promising strategy against some carcinomas." (PMID 28619062, 2017). "Our study reveals a novel mechanistic connection between activated Akt and the UPS through regulating of USP14 phosphorylation, which can impact global proteostasis in PTEN-negative cancer cells." (PMID 26523394, 2015). "In addition, exploring the functional significance of USP14 and FABP5 in various cancer types will enhance our overall comprehension of their functions in cancer biology on a broad scale." (PMID 39928282, 2025). "In summary, this study uncovers a novel regulatory axis involving USP14 and BAG4 in cancer cells." (PMID 40316942, 2025). "Furthermore, DUB inhibitors targeting USP14 and UCHL5 downregulate ERα expression and induce cancer cell apoptosis, providing a prospective strategy for ER-positive BCa treatment." (PMID 38177530, 2024). "Studies have shown that inhibiting USP14 can regulate amino acid metabolism balance and fatty acid oxidation, leading to an evaluation in CD8 + T cells and a declined infiltration of promoting-cancer M2 macrophages." (PMID 37658402, 2023). "USP14 further plays a role in tumor growth, and the inhibition of USP14 by compounds such as IU1 may affect cancer cell migration and invasion." (PMID 37711852, 2023). "IHC staining of USP14 in our FUSCC cohort showed that the IHC score was significantly higher in carcinoma tissues than normal tissues, and the expression of SDC2 was significantly higher in the High-USP14 group (IHC score > 4) than the Low-USP14 group of GC tumor specimens." (PMID 37496999, 2023). "Moreover, USP14 directly deubiquitinates and stabilizes IDO1 to protect it against ubiquitination and proteosome-mediated degradation in cancer cells." (PMID 36163134, 2022). "In various cancers, the expression of UCHL5 and USP14 is upregulated." (PMID 33919439, 2021). "If USP14 negatively affects FASN levels in cancer cells, it could be predicted that inhibition of both USP14 and FASN using siRNAs or inhibitors would restore reduced cancer cell viability by inhibiting only FASN." (PMID 34948233, 2021). "However, inhibition of both FASN and USP14 had no significant synergistic effect on cancer cell proliferation and, surprisingly, it was confirmed that USP14 negatively regulates the protein level and activity of FASN in cancer cells." (PMID 34948233, 2021). "This can be interpreted as meaning that inhibition of USP14 does not help in terms of modulating the metabolic pathways in the cancer cells by FASN." (PMID 34948233, 2021). "Taken together, the results reveal that USP14 negatively regulates FASN levels unexpectedly in the cancer cells, and as a result, inhibition of USP14 was not conducive to cancer cell death through inhibition of FASN." (PMID 34948233, 2021). "Furthermore, H2A deubiquitinases, such as BAP1, USP14 and USP28, have been shown to suppress proliferation and increase radiosensitization in human cancers." (PMID 31761786, 2019). "DUBs are critical key players in diverse processes such as (i) spermatogenesis (e.g. USP2, USP8, USP9y, USP14, USP26, Uchl-1, Uchl-3 and CYLD), (ii) cancer biology (e.g. USP7, USP10 and USP11), and (iii) stemness and differentiation (e.g. USP7, USP9x, USP22, USP44 and Psmd14)." (PMID 28659380, 2017). "Since we have identified that the bio-target of ZnPT involves USP14 and UCHL5, whether overexpression of USP14 or UCHL5 could add resistance of cancer cells to ZnPT should be investigated in the future." (PMID 28086217, 2017). "However, the biological functions of USP14 in cancer-related glycolysis have not been explored extensively." (PMID 38388430, 2024). "For example, since 2015, several DUBs-targeted agents, including VLX1570 (targeting USP14), P22077 (targeting USP7/USP10/USP47), P5091 (targeting USP7/USP47), and spautin-1 (targeting USP10/USP13), have been investigated in the clinic to treat certain types of cancers." (PMID 39522000, 2024).